MTOR (mechanistic target of rapamycin kinase)
Diseases named in the same sentence as MTOR in open-access papers (continued):
Sharing a sentence is not in itself a finding about the gene and the disease.
age-related hearing loss (2 papers, 2020 to 2022). "For instance, several antioxidant genes, including SOD2, GST or UCP, have been associated to age-related hearing loss and genetic mouse models deficient for antioxidant genes, including Nrf2, Sod1 or genes regulating the mTOR pathway, show accelerated age-related hearing loss." (PMID 32000019, 2020). "In the PPI network, autophagy-related genes ATG5, ATG7 showed the highest node scores in mild presbycusis; whereas MTOR, BECN1 showed the highest scores in severe presbycusis." (PMID 35463035, 2022).
alcohol abuse (2 papers, 2020 to 2021). The use of alcoholic beverages to excess, either on individual occasions ("binge drinking") or as a regular practice. "Accumulating evidence that indicates the role of the mTOR signaling pathway in long-term potentiation fueled the search to understand the role of mTOR signaling pathway and rapamycin in the synaptic plasticity-mediated clinical model such as the reinstatement of drug addiction and alcohol abuse." (PMID 32111062, 2020).
alcoholic hepatitis (2 papers, 2017 to 2024). Acute hepatitis resulting from ingestion of alcohol. "Another study showed that, PA-loaded mesoporous silicon nanoparticles through mammalian target of rapamycin (mTOR)-mediated autophagy pathway could be a possible protective strategy to improve alcoholic hepatitis." (PMID 39512816, 2024).
anal tumor (2 papers, 2022 to 2025). "Mice were monitored for overt anal tumor development and anal tissue was assessed for histology and markers of PI3K and mTOR activity (pAKT and pS6, respectively)." (PMID 36683775, 2022).
angioedema (2 papers, 2020 to 2024). Swelling involving the deep dermis, subcutaneous, or submucosal tissues, representing localized edema. "Angioedema is a concerning side effect associated with the use of mTOR-Is, supported by empirical evidence derived from case series and anecdotal reports." (PMID 38205154, 2024). "In recognition of the elevated risk of angioedema associated with the concomitant administration of ACE inhibitors and mTOR-Is, including sirolimus and everolimus, the FDA issued a warning, underlining the critical importance of these findings." (PMID 38205154, 2024). "All these findings underscore the intricate interplay between ACE inhibitors, mTOR-Is, and the occurrence of angioedema." (PMID 38205154, 2024). "Concomitant therapy with mTOR inhibitors (OR 4.3 [1.0–17.9]) and fibrinolytics (OR 7.8 [1.1–57.2]) was reported more often in ACEi versus ARBs angioedema reports." (PMID 32214375, 2020). "Additionally, a randomized study involving heart transplant recipients demonstrated that those receiving ACE inhibitors and mTOR inhibitors had a 50–100 times higher incidence of angioedema compared to those on conventional immunosuppression therapy." (PMID 38205154, 2024). "Emerging anecdotal cases have brought attention to the intricate interaction between mTOR-Is and ACE inhibitors, leading to the development of angioedema." (PMID 38205154, 2024).
Aortic dissection (2 papers, 2024 to 2025). Aortic dissection refers to a tear in the intimal layer of the aorta causing a separation between the intima and the medial layers of the aorta. "For example, metabolic reprogramming of VSMCs was suggested to play a critical role in the pathogenesis of thoracic aortic dissection involving mitochondrial ROS damage and altered mTOR signalling." (PMID 38418756, 2024).
apocrine carcinoma (2 papers, 2022 to 2023). "PI3K/Akt/mTOR pathway inhibitors were successfully applied in the therapy of apocrine carcinoma and proliferating trichilemmal tumors." (PMID 35205753, 2022). "Approximately 90% of apocrine carcinomas involve genetic abnormalities in the PI3K/mTOR pathway, and this may suppress T-cell infiltration." (PMID 36385236, 2023).
arteriovenous malformation (2 papers, 2024 to 2026). "mTOR and PI3Kα inhibitors such as sirolimus and alpelisib have shown promising efficacy in slow-flow VMs, while reports have suggested that MAPK inhibitors such as trametinib may improve arteriovenous malformations." (PMID 41272322, 2026).
arteritis (2 papers, 2015 to 2024). An inflammatory process affecting an artery. "Notably, the emergence of SMC-derived luminal myofibroblasts—in both mice and patients with KD, Takayasu’s arteritis and Giant Cell arteritis—coincided with activation of the mechanistic target of rapamycin (mTOR) signalling pathway." (PMID 39271773, 2024).
arthropathy (2 papers, 2014 to 2024). Any disorder of the joints. "In conclusion, our results demonstrated that the intra-articular injection of rapamycin reduce mTOR expression, which leads to a delay in cartilage degradation after surgically inducing joint instability." (PMID 25403236, 2014). "IVW-MR analysis also found evidence for the casual association between MTOR, ARNTL, KRAS, and RPSA with UC along with arthropathy ((OR 0.334, 95%CI 0.239–0.467; OR 0.607, 95%CI 0.499–0.739; OR 1.537, 95%CI 1.927–1.980; OR 1.756, 95%CI 1.133–2.724, respectively)." (PMID 38302916, 2024).
Ascites (2 papers, 2009 to 2021). Accumulation of fluid in the peritoneal cavity (between the layers of the peritoneum that lines the abdomen). "An activated tumour cell VEGFR2/AKT/mTOR pathway was associated with increased incidence of ascites (χ2, P=0.002) and reduced overall survival of cisplatin–taxane-based patients with serous histology (N=32, log-rank test, P=0.04)." (PMID 19240722, 2009).
atrial fibrillation (2 papers, 2024 to 2025). A disorder characterized by an electrocardiographic finding of a supraventricular arrhythmia characterized by the replacement of consistent P waves by rapid oscillations or fibrillatory waves that vary in size, shape and timing and are accompanied by an irregular ventricular response. "Studies on rabbits utilizing ziprasidone, which induces atrial arrhythmia, including atrial fibrillation (AF), have shown increased activation of the NLRP3 inflammasome and ROS production via the PI3K/Akt/mTOR pathway." (PMID 39594530, 2024).
atypical hemolytic-uremic syndrome (2 papers, 2024 to 2025). A rare, genetic thrombotic microangiopathy due to dysregulation of the alternative complement pathway and characterized by the triad of hemolytic anemia, thrombocytopenia, and acute renal dysfunction. "Although atypical HUS (aHUS) represents the first cause of recurrent posttransplant TMA, etiologies of de novo posttransplant TMA commonly include immunosuppressive medications (i.e., CNI and mTOR inhibitors), antibody-mediated rejection, viral infections, and malignant hypertension." (PMID 41278354, 2025).
Azoospermia (2 papers, 2014 to 2025). Absence of any measurable level of sperm,whereby spermatozoa cannot be observed even after centrifugation of the semen pellet. "Activation of mTOR results in translation of the RNA binding protein Dazl (Deleted in azoospermia-like), and Dazl subsequently binds the 3′UTR of Grsf1 to enhance translation." (PMID 25184340, 2014).
Brain atrophy (2 papers, 2020 to 2025). Partial or complete wasting (loss) of brain tissue that was once present. "A major goal of this study was to characterize the early- versus late-stage effects of heavy ethanol consumption on the insulin/IGF-1-Akt-mTOR pathway in relation to brain atrophy." (PMID 40149949, 2025). "Further probing of downstream mediators was conducted to determine the mechanistic role of dysregulated mTOR signaling in relation to brain atrophy in ARBD." (PMID 40149949, 2025). "mTOR phosphorylates S6K1 (a key regulator of cell volume), therefore mHTT-related impairment of mTOR may account for the brain atrophy in HD." (PMID 31940909, 2020).
breast angiosarcoma (2 papers, 2023 to 2024). A malignant vascular neoplasm arising from the breast. "The PIK3CA/AKT/mTOR pathway is either directly or indirectly involved in the development of breast angiosarcomas." (PMID 38015377, 2023).
C. perfringens infection (2 papers, 2024 to 2025). "In this study, we aimed to investigate the cellular and molecular mechanisms of C. perfringens infection using chicken NE, the mTOR inhibitor rapamycin, DCA, and a cell culture system." (PMID 40284599, 2025). "Altogether, these results support STING involvement in trained immunity which protects against C. perfringens infection via mTOR signaling." (PMID 38622656, 2024). "Herein, we demonstrate that STING-dependent trained immunity contributes to host defense against C. perfringens infection via mTOR signaling." (PMID 38622656, 2024). "In our study, there is a novel finding that STING-dependent trained immunity protected against C. perfringens infection by regulating mTOR signaling." (PMID 38622656, 2024). "Here, we show that stimulator of interferon genes (STING)-dependent trained immunity protected against C. perfringens infection through mTOR signaling." (PMID 38622656, 2024). "Future research on the role of tissue-specific mTOR in C. perfringens infection could provide additional mechanistic insights." (PMID 40284599, 2025). "Hence, our investigation highlighted the significance of STING in promoting trained immunity induction for host defense against C. perfringens infection via the mTOR signaling pathway." (PMID 38622656, 2024).
calcification (2 papers, 2022 to 2023). Process by which organic tissue becomes hardened by the physiologic deposit of calcium salts. "We have also shown that CT-Exo could protect VSMCs against calcification/senescence by activating the AMPK/mTOR autophagy pathway and protecting mice against medial arterial calcification." (PMID 37461031, 2023).
campylobacteriosis (2 papers, 2023 to 2025). Infections with bacteria of the genus campylobacter. "Blocking the PI3K downstream target mTOR by rapamycin reduces neutrophil migration-mediated crypt abscesses and inflammation in mouse campylobacteriosis." (PMID 40284599, 2025). "Interestingly, mTOR is the cellular target for the immune suppressor rapamycin (sirolimus) that has been shown to potently ameliorate acute campylobacteriosis in infected IL-10−/− mice." (PMID 36830689, 2023).
Candida infection (2 papers, 2019 to 2020). "Collectively, these results showed that IL-1β/IL-1R signaling is required for promoting mTOR activation and IL-17A induction in Foxp3+ cells during Candida infection in oral mucosa." (PMID 33240286, 2020). "Candida infection promoted mTOR phospohorylation in WT but not in IL-1R1-/- Tregsin vivo." (PMID 33240286, 2020).
cardiac arrest (2 papers, 2018 to 2019). Cessation of breathing and/or cardiac function. "By using a reversible model of cardiac arrest in rat, which was developed in our laboratory, we investigated the time-dependent phosphorylation level of LKB1 (Ser431), AMPK (Thr172) and mTOR (Ser2448) along with their non-phosphorylated forms (total proteins) in brain, heart, liver and kidney." (PMID 29921218, 2018).
cardiac interstitial fibrosis (2 papers, 2021 to 2025). "In cardiac-specific human NADPH oxidase 4 (Nox4) transgenic mice, an increase in NOX4 protein expression leads to an increase in ROS generation with cardiac interstitial fibrosis through activation of protein kinase B-mechanistic target of rapamycin (Akt-mTOR) and NF-κB signaling pathways." (PMID 34297135, 2021).
carotid atherosclerosis (2 papers, 2025). A thickening and loss of elasticity of the walls of carotid arteries that occur with formation of atherosclerotic plaques. "Furthermore, in an animal model of carotid atherosclerosis, berberine reduced the atherosclerotic plaque area, lipid accumulation, neointimal formation and cell apoptosis in carotid arteries by regulating the PI3K/AKT/mTOR signaling pathway, thereby improving carotid atherosclerosis." (PMID 41300435, 2025).
cavernoma (2 papers, 2022 to 2025). "P-S6, a downstream effector of AKT/mTOR, was no longer active in most of the adult cavernoma-like vascular lesions we observed in mice with mutant Pik3ca in cells having once expressed Egr2/Krox20." (PMID 36353506, 2022).
cholestasis (2 papers, 2022). Impairment of the bile flow caused by obstruction within the liver, or outside the liver in the bile duct system. "Our results clearly demonstrate that cholestasis-induced Sestrin2 expression suppresses mTOR activity by activating AMPK." (PMID 35260799, 2022). "The inhibitory effect of Sestrin2 on hepatic ER stress during cholestasis may be the result of protein translation inhibition through the AMPK/mTOR pathway." (PMID 35260799, 2022). "Taken together, these findings suggested that hepatocytes responded to cholestasis by highly inactivating YAP and activating mTOR signaling and, furthermore, Nrf2 might not play a major role in mediating these responses." (PMID 35696363, 2022).
Cholestatic liver disease (2 papers, 2020 to 2025). "In cases of cholestatic liver disease, BM-MSCs mitigated the activation of hepatic stellate cells (HSCs) through the regulation of autophagy via the PI3K/AKT/mTOR pathway." (PMID 41390431, 2025).
chromophobe carcinoma (2 papers, 2025). "The combination of a tyrosine kinase inhibitor (lenvatinib 18mg) with an inhibitor of the mTOR pathway (everolimus 5mg) was approved in a phase 2 multicenter trial including 31 patients, nine of whom had chromophobe carcinoma." (PMID 40438847, 2025).
chronic liver failure (2 papers, 2019 to 2025). Liver failure that develops slowly and gradually for some time, possibly for years, often as the result of cirrhosis, or malnutrition. "In acute or chronic liver failure, studies have found that Mfn2 can significantly attenuate the symptoms of liver failure, improve the expression of autophagy related proteins, and downregulate the expression of apoptosis-related proteins through the PI3K/Akt/mTOR signaling pathway." (PMID 40362804, 2025).
chronic lymphoid leukemias (2 papers, 2013 to 2017). "Rather, we believe that several different pathways and pro-oncogenic molecules contribute to expression of PI3-kinase, mTOR, and BCL-2 family members in lymphoid leukemias." (PMID 28978065, 2017).
chronic pancreatitis (2 papers, 2022 to 2024). A chronic inflammatory process causing damage and fibrosis of the pancreatic parenchyma. "We also demonstrate that the protective role of miR-301a deletion in chronic pancreatitis and PanIN is dependent on two downstream axes: Tsc1/mTOR and Gadd45g/Stat3." (PMID 35211358, 2022).
Chylothorax (2 papers, 2025). The presence of chyle in the thoracic cavity. "This prospective case series describes seven infants with congenital chylothorax and/or hydrops fetalis due to CCLA, all of whom were treated with either an mTOR and/or MEK inhibitor and demonstrated remarkable clinical improvement within weeks after initiation." (PMID 40835771, 2025).
cleft palate (2 papers, 2019 to 2024). Cleft palate is a fissure type embryopathy that affects the soft and hard palate to varying degrees. "Activation of the PTEN/AKT/mTOR pathway may prevent the formation of cleft palate." (PMID 31358051, 2019).
CLOVES syndrome (2 papers, 2021 to 2023). A syndromic disease characterized by Congenital Lipomatous Overgrowth, progressive, complex and mixed truncal Vascular malformations, Epidermal nevi, and Skeletal anomaly. "In this study, we reported a patient with CLOVES syndrome caused by a somatic frameshift mutation c.3206_3207insG in PIK3CA which results in gain of function by provoking the PI3K/AKT/mTOR pathway." (PMID 34074347, 2021). "Our results suggested that ARQ092 could be considered as a potential medication measurement for CLOVES syndrome or other disorders caused by hyperactivation of the PI3K/AKT/mTOR pathway." (PMID 34074347, 2021). "We aim to investigate underlying mutation and its pathogenicity in a patient with CLOVES syndrome and to evaluate the inhibitory effects of the PI3K/AKT/mTOR pathway inhibitors." (PMID 34074347, 2021). "We report a case of CLOVES syndrome due to a frameshift mutation c.3206_3207insG in PIK3CA, which was confirmed to be gain-of-function by provoking PI3K/AKT/mTOR signaling pathway." (PMID 34074347, 2021). "We have identified the first frameshift mutation in PIK3CA that causes CLOVES syndrome, which was confirmed to overactive PI3K/AKT/mTOR pathway by transient transfection assays." (PMID 34074347, 2021). "Notably, Rapamycin (sirolimus), an mTOR inhibitor, has demonstrated its efficacy in various instances involving patients with CLOVES syndrome, leading to improvements in adipose overgrowth, vascular irregularities, and overall quality of life." (PMID 38229701, 2023).
cutaneous leishmaniasis (2 papers, 2018 to 2020). Leishmaniasis affecting the skin. "To summarize, we propose that the adjuvant effects of rapamycin and one of the mTOR inhibitor GSK-2126458 can be exploited for the treatment of cutaneous leishmaniasis." (PMID 30133440, 2018). "Recently, the utilization of SIR as a treatment for L. major cutaneous leishmaniasis in mice led to a significant reduction of parasite burden in draining lymph nodes, also confirming that the use of mTOR inhibitors could be a new strategy to limit the growth of different Leishmania species." (PMID 32517744, 2020).
developmental and epileptic encephalopathies (2 papers, 2021 to 2025). "Together, these data support a model in which immune activation and mTOR pathway overactivity act synergistically to impair neuronal circuit maturation, lower seizure thresholds, and drive the developmental epileptic encephalopathy that defines WS." (PMID 41470225, 2025). "Increased signaling through interleukin 1 receptor pathways and toll like receptors has been documented in developmental epileptic encephalopathies, including disorders marked by mTOR dysregulation." (PMID 41470225, 2025).
dystroglycanopathy (2 papers, 2016 to 2023). "In another study, disrupting the interaction between αDG and laminin was found to induce apoptosis and reduce Akt phosphorylation while treatment of a fukutin-deficient dystroglycanopathy with the mTOR inhibitor RAPA was found to increase myofiber size." (PMID 36878377, 2023). "We found evidence of elevated mTOR activation in later-stage dystroglycanopathy muscle of Fktn-deficient mice." (PMID 27257474, 2016). "Future studies will be important to define the best pharmacological agents and molecular targets in the mTOR pathway for skeletal muscle improvements in dystroglycanopathies." (PMID 27257474, 2016). "To determine whether Akt/mTOR signaling is altered in dystroglycanopathy mice, we examined the activation status of pathway proteins in fasted Myf5/Fktn KO muscle from mice aged 17–25 weeks, an age range with substantive remodeling of the muscle compartment." (PMID 27257474, 2016).
Emery-Dreifuss muscular dystrophy (2 papers, 2019 to 2020). Emery-Dreifuss muscular dystrophy (EDMD) is characterized by muscular weakness and atrophy, with early joint contractures and cardiomyopathy. "Indeed, hyper-activation of protein kinase B (AKT)/mTOR signaling has been demonstrated in muscular laminopathies, and rescue of mTOR-regulated pathways increases lifespan in animal models of Emery-Dreifuss muscular dystrophy." (PMID 30781376, 2019).
emotional dysregulation (2 papers, 2021 to 2024). "KEGG pathway analyses revealed additional implicated pathways, including mTOR and insulin signaling, which play a crucial role in cellular growth and metabolism, highlighting the extensive physiological effects of PTSD beyond psychological distress." (PMID 39334086, 2024).
endometrial adenocarcinoma (2 papers, 2014 to 2021). "Although high AKT activity is well documented in endometrial adenocarcinomas, very little data exist on the role of the mTOR pathway in this type of cancer." (PMID 24526917, 2014).